RIMBP3C (RIMS binding protein 3C)
Description:
Probable component of the manchette, a microtubule-based structure which plays a key role in sperm head morphogenesis during late stages of sperm development.
Synonyms: RIM-BP3.3; RIMBP3.3
Tractability: PROTAC: ubiquitination databases record sites on it.
Gene: Protein-coding gene on chromosome 22 (21,545,666 to 21,551,461, reverse strand). Ensembl gene ENSG00000183246.
Subcellular location: Cytoplasm, cytoskeleton
Subcellular location (Human Protein Atlas): Plasma membrane; Vesicles
Gene Ontology:
Molecular function: benzodiazepine receptor binding
Biological process: fertilization; neuromuscular synaptic transmission; spermatid development
Cellular component: manchette; nucleus; cytoskeleton
Homologues: Orthologues: rat Rimbp3 (64% identical), mouse Rimbp3 (63% identical), Drosophila melanogaster Rbp (14% identical), Caenorhabditis elegans rimb-1 (14% identical). Paralogues in human: RIMBP3B (99% identical), RIMBP3 (99% identical), TSPOAP1 (29% identical), RIMBP2 (17% identical).
Diseases named in the same sentence as RIMBP3C in open-access papers:
RIMBP3C is named in the same sentence as 3 diseases in open-access papers, as found by Europe PMC text mining. Sharing a sentence is not in itself a finding about the gene and the disease. The quoted sentences say what the papers report.
oligospermia (1 paper, 2017). Decreased number of spermatozoa in the semen. "Eight genes among 817 genes (0.01%) (ADAM32, DYNLRB2, KLHL10, RIMBP3C, SEPT12, TIMD4, TSACC and TTC25) were common between MArrest and teratospermia, and three genes among 435 genes (0.007%) (HRASLS, LIMS3 and MRPL42) were common between oligospermia and teratospermia." (PMID 29150651, 2017).
tumor (1 paper, 2021). "The implication in sunitinib resistance, tumor‐infiltrating, and the progression and development in ccRCC was first uncovered for CRYBB1 and the prognostic implication in ccRCC was also first demonstrated for RIMBP3C in this study." (PMID 34402193, 2021).
RIMBP3C also shares sentences with these, for which no sentence is quoted: teratospermia (1 paper).